ATF2 (activating transcription factor 2)
Diseases named in the same sentence as ATF2 in open-access papers (continued):
Sharing a sentence is not in itself a finding about the gene and the disease.
Cognitive impairment (3 papers, 2020 to 2024). Abnormal cognition is characterized by deficits in thinking, reasoning, or remembering. "Considering that ATF2 is critical for hippocampal neurogenesis and memory processing, we speculated that the expression of ATF2 is responsible for inflammation and neuronal apoptosis in the hippocampus associated with cognitive impairment." (PMID 37973625, 2024). "Both the ROS system and p38MAPK/ATF2 pathway are involved in the regulation of isoflurane-induced cognitive impairment in aged mice." (PMID 33519423, 2020). "Therefore, in this study, we hypothesized that atorvastatin pretreatment could inhibit isoflurane-induced apoptosis and cognitive impairment in aged mice, partly by inhibiting the ROS-p38MAPK/ATF-2 pathway." (PMID 33519423, 2020). "Isoflurane induces cognitive impairment of aged mice and induces inflammation and oxidative stress in BV2 cells through the ROS-p38MAPK/ATF2 pathway." (PMID 34895041, 2021).
depression (3 papers, 2018 to 2022). "As a result, there is an increase in the transcription efficiency of ATF-2, thus triggering COX2-mediated neuroinflammation which is associated with depression." (PMID 30526621, 2018). "Furthermore, overexpression of βCaMΚΙΙ in the CA1 region of wild-type rats via AAV-virus injection effectively induced depression-like behaviors and strongly increased the phosphorylation levels of p38 MAPK and the transcription factors CREB and ATF-2." (PMID 30526621, 2018). "However, whether ATF2 functions as a downstream molecule of βCaMΚΙΙ to upregulate COX-2 transcription and hence facilitate inflammatory responses related to depression remains unknown." (PMID 30526621, 2018).
diabetes (3 papers, 2019 to 2021). "Also, the intron microRNA hsa-miR-933 is potentially associated with the development of neurodegenerative diseases and diabetes, and its important role in regulating ATF2 target genes could explain the observed association to some extent." (PMID 34595235, 2021). "In conclusion, the present study demonstrated that Ufm 1 activated NF-κB pathway by down-regulating LZAP in macrophage of diabetes, and its expression and activation were regulated by JNK/ATF2 and c-Jun pathway." (PMID 31829413, 2020). "We also confirmed that treatment with dexamethasone and triamcinolone acetonide reduced diabetes‐induced phosphorylation of AKT, ERK1/2, ATF2, c‐Fos and c‐Jun as well as galectin‐1 protein levels." (PMID 31328390, 2019). "In conclusion, the present study demonstrated that Ufm 1 could activate NF-κB pathway by down-regulating LZAP in macrophage of diabetes, and its expression and activation were regulated by JNK/ATF2 and c-Jun pathway." (PMID 31829413, 2020). "In conclusion, the present study demonstrated that LPS induced the overexpression of Ufm1 through JNK/ATF2 and c-Jun pathway; the highly expressed Ufm1 further activated the NF-κB pathway and resulted in inflammatory response by decreasing LZAP expression in macrophage of diabetes." (PMID 31829413, 2020).
endometrial carcinoma (3 papers, 2020 to 2023). A malignant tumor arising from the epithelium that lines the cavity of the uterine body. "Exons 2 and 3 of TNFRSF21 transcripts were back-spliced to produce circTNFRSF21 that can promote endometrial carcinoma pathogenesis by regulating the miR-1227-MAPK13/ATF2 axis." (PMID 38139387, 2023). "Mechanically, circTNFRSF21 acts as a sponge of miR-1227 to rescue MAPK13/ATF2 signaling pathway activity in endometrial cancer cells." (PMID 34552882, 2021).
Hepatitis (3 papers, 2013 to 2020). Inflammation of the liver. "In LPS-induced hepatitis and HCl/EtOH-induced gastritis, we recently observed significant activation of ATF2 (unpublished data), suggesting that ATF2 participates in these inflammatory processes." (PMID 25049453, 2014). "We found that, in mice with hepatitis induced by treatment for 7 days with D-gal/LPS, levels of activated ATF2 were significantly higher than in the control group." (PMID 25049453, 2014). "During treatment with ATF2 inhibitors, symptoms of hepatitis in the mice regressed in parallel with a decline in activated ATF2." (PMID 25049453, 2014). "In agreement with in vitro effect, AG strongly suppressed ATF-2 phosphorylation in the LPS-induced hepatitis mouse model." (PMID 23840248, 2013).
metastatic tumors (3 papers, 2010 to 2024). "In silico analysis of gene expression omnibus (GEO) series (GSE) revealed decreased ATF2 expression in metastatic tumors." (PMID 35838828, 2022).
cardiac hypertrophy (2 papers, 2021 to 2024). "Finally, TGFβ induces cardiac hypertrophy by PKC-dependent ATF2 activation." (PMID 34272480, 2021).
Desminopathy (2 papers, 2016 to 2021). "Desmin-positive protein aggregates correlate with high levels of ATF2, voltage-dependent anion-selective channel protein 1 (VDAC1), and BCL2 Associated X (BAX) in muscle fibers of desminopathy patients." (PMID 34272480, 2021). "We have found that ATF2 deposited in the skeletal muscle fibers with desmin deposition of desminopathy patients and animal models, which suggests that desmin deposition in muscle fibers and tends to apoptosis." (PMID 27941998, 2016). "Meanwhile apoptosis related proteins bax and ATF2 were involved in desminopathy patients and desminopathy rat model, but not bcl-2, bcl-xl or HK2.VDAC1 and desmin are closely relevant in the tissue splices of deminopathies patients and rats with desminopathy at protein lever." (PMID 27941998, 2016). "Moreover, apoptotic proteins are also involved in the desminopathies, like bax, ATF2, but not bcl-2, bcl-xl or HK2." (PMID 27941998, 2016).
endothelial dysfunction (2 papers, 2025). In vascular diseases, endothelial dysfunction is a systemic pathological state of the endothelium (the inner lining of blood vessels) and can be broadly defined as an imbalance between vasodilating and vasoconstricting substances produced by (or acting on) the endothelium. "It controls ACE2, possibly by reducing nuclear p-ATF2 accumulation in CC-induced endothelial dysfunction, a known risk factor for hypertension." (PMID 41567643, 2025). "SIRT6 regulates ACE2 by blocking the accumulation of nucleus p-ATF2 in CC-induced endothelial dysfunction." (PMID 41567643, 2025).
Hyperglycemia (2 papers, 2020 to 2024). An increased concentration of glucose in the blood. "miR-933 might control hyperglycemia and hyperinsulinism by regulating ATF2 target genes, potentially playing a role in type II diabetes mellitus pathogenesis." (PMID 39882071, 2024).
hyperinsulinism (2 papers, 2020 to 2024). Abnormally high levels of insulin in the blood. "Insulin itself can create a positive feedback loop by activating ATF2 in this pathway solely or mediated by MAPK8 (preceded by MAP4K4) or PRKCE which can eventually lead to hyperinsulinemia." (PMID 32993798, 2020). "Our approach delineated that hsa-miR-933 might control the hyperglycemic condition and hyperinsulinism by regulating ATF2 target genes MAP4K4, PRKCE, PEA15, BDNF, PRKACB, and GNAS which can otherwise lead to the development of type II diabetes mellitus." (PMID 32993798, 2020).
Kashin-Beck disease (2 papers, 2013 to 2022). Disabling osteochondrodysplasia with osteosclerosis, cone-shaped metaphysis, and shortening of the diaphysis. "In Kashin-Beck disease, increased phosphorylation of ATF2 is associated with chondrocyte apoptosis, consistent with the previously defined role in osteoclast differentiation." (PMID 35784175, 2022). "The purpose of the study was to understand the function and expression of ATF2 by JNK and p38 signal pathways in the chondrocytes apoptosis of articular cartilage of the Kashin-Beck disease (KBD)." (PMID 23866832, 2013).
lymphoma (2 papers, 2013 to 2014). A malignant (clonal) proliferation of B- lymphocytes or T- lymphocytes which involves the lymph nodes, bone marrow and/or extranodal sites. "FOXM1 is a potential therapeutic target in mature B cell tumors and ATF2 has been recently found to be highly disregulated in lymphoma." (PMID 25170874, 2014). "Moreover, knockdown of ATF2 expression in lymphoma cells phenocopied the inhibitory effects of DN-TCF4 on the expression of target genes associated with the Wnt pathway and on cell growth." (PMID 23966864, 2013). "We established that both TCF1 and LEF1 interact with ATF2 transcription factors to promote TCF/LEF activity, and inhibition of such activity using either DN-TCF4 or shATF2/7 decreased the expression of Wnt target genes, as well as lymphoma cell growth." (PMID 23966864, 2013).
myeloma (2 papers, 2023 to 2024). "Active JNK phosphorylates nuclear transcription factors such as c-Jun and ATF2, leading to the transcription of target genes that protect myeloma cells from apoptosis." (PMID 39198400, 2024).
neuroblastoma (2 papers, 2017 to 2022). Neuroblastoma (NB) is the most common solid, extracranial childhood tumor. "The consequences of ERK dephosphorylation could be also relevant in neuroblastoma, where ERK promotes the activity of various transcription factors such as CREB, Myc, Jun, Fos, Elk-1, Ets, Msk and Atf2." (PMID 36589747, 2022).
schizophrenia (2 papers, 2015 to 2024). A major psychotic disorder characterized by abnormalities in the perception or expression of reality. "Pathway analysis of the NeuN+ TFs affected by age in the AT-schizophrenia/control cohort led to the top pathway ‘NGF-simulated transcription’ (p-value 8.04×10–8), including the TFs EGR2 and ATF2." (PMID 38648100, 2024).
squamous carcinoma (2 papers, 2015 to 2018). "For example, hypoxia could activate the JNK and p38 stress kinases in human squamous carcinoma cells and further leads to phosphorylation of transcription factor ATF-2." (PMID 26711814, 2015). "In the squamous carcinoma cell line SCC-9, ATF2 translocates to the mitochondria following genotoxic stress and disrupts the Hexokinase 1 (HK1)—Voltage dependent anion channel 1 (VDAC1) complex, thereby compromising mitochondrial membrane pore permeability and promoting apoptosis." (PMID 30497386, 2018).
type 2 diabetes mellitus (2 papers, 2020 to 2024). A type of diabetes mellitus that is characterized by insulin resistance or desensitization and increased blood glucose levels. "Insulin overproduction also leads to the overexpression of other ATF2 target genes that lead to β-pancreatic cell dysfunction—pathophysiology of type II diabetes mellitus." (PMID 32993798, 2020). "With this correspondence, the role of intronic miRNA hsa-miR-933’s functional regulation on its host gene ATF2 can provide valuable insight into the progression and control of type II diabetes mellitus." (PMID 32993798, 2020). "ATF2 targets genes are involved in insulin action, β cell function, and type II diabetes mellitus." (PMID 32993798, 2020). "From this information, it can be considered for the analysis if hsa-miR-933 can regulate the overexpressed PEA15, downregulated BDNF, or other ATF2 target genes (PRKACB, GNAS, PRKCE, and MAP4K4) to control type II diabetes mellitus." (PMID 32993798, 2020).
achondroplasia (1 paper, 2023). Achondroplasia is the most common form of chondrodysplasia, characterized by rhizomelia, exaggerated lumbar lordosis, brachydactyly, and macrocephaly with frontal bossing and midface hypoplasia. "Mice lacking ATF2 displayed achondroplasia, and ATF2 also regulated cell proliferation by targeting cyclin A." (PMID 37889831, 2023).
acute lymphoblastic leukemia (1 paper, 2023). Leukemia with an acute onset, characterized by the presence of lymphoblasts in the bone marrow and the peripheral blood. "Moreover, ATF2 was shown to induce cancer genesis and progression in T-cell acute lymphoblastic leukemia (T-ALL)." (PMID 37955015, 2023).
alcoholism (1 paper, 2019). "ATF2 is in the backbone network and is involved in all three substance diseases (alcoholism, amphetamine addiction, and cocaine addiction) in the KEGG pathways." (PMID 30899073, 2019). "(Alcoholism, amphetamine addiction, cocaine addiction) ATF2, CREB1, CREB5, and FOSB in all three substance disease KEGG pathways are suspected be related with CREB and FOS family, and JUN." (PMID 30899073, 2019). "Seven nodes including JUN, FOS, RELA, MAPK1, ATF2, HRAS, and CREB1 in the backbone are the recorded genes of alcoholism, amphetamine addiction, or cocaine addiction in the KEGG pathways." (PMID 30899073, 2019). "Moreover, ATF2, CREB1, CREB5, and FOSB in all three substance diseases (alcoholism, amphetamine, and cocaine addiction pathways)." (PMID 30899073, 2019).
allergic asthma (1 paper, 2023). A asthma with a basis in a pathological type I hypersensitivity reaction. "In addition, silencing ATF2 attenuated the ability of MSCs to alleviate airway inflammatory responses in an ovalbumin-induced mouse model of allergic asthma." (PMID 36765266, 2023). "We next investigated whether MSC priming with ATF2 activation could be beneficial for treating allergic asthma." (PMID 36765266, 2023). "Collectively, our findings suggest that ATF2 is a novel modulator of GSH dynamics that determines the core functionality and therapeutic potency of MSCs used to treat allergic asthma." (PMID 36765266, 2023). "The results presented here demonstrate that ATF2 is a novel mediator of GSH dynamics in MSCs that acts via interplay with the NRF2 signaling cascade, thereby affecting the functionality and therapeutic potency of MSCs toward allergic asthma." (PMID 36765266, 2023). "In this study, ATF2 played a crucial role in the beneficial effects of the PFO procedure based on the combination of three small molecules, AA2G, S1P, and VPA, which significantly improved the therapeutic potency of MSCs from different sources for treating allergic asthma." (PMID 36765266, 2023).
angiosarcoma (1 paper, 2021). A malignant tumor arising from the endothelial cells of the blood vessels. "EBNA1 activating AP‐1 transcription factor pathway by binding to ATF2 and elevated expression of AP‐1 targeting VEGF; SARS and ROCK1/2 are unique regulators in angiogenesis and angiosarcoma tumour progression." (PMID 33586248, 2021).
Anxiety (1 paper, 2023). Intense feelings of nervousness, tension, or panic often arise in response to interpersonal stresses. "The largest number of DEGs associated with neurogenesis and making the largest contribution to C_A20 differences are associated with an abnormal anxiety-related response (Nr1d1, Fmr1, Atf2, and Pten)." (PMID 36769363, 2023).
Arthritis (1 paper, 2022). Inflammation of a joint. "In terms of anti-arthritis, ginsenoside Rc (40 μg/mL and 60 μg/mL) exhibits significant activity, which can alleviate inflammation by inhibiting the targeted binding kinase 1/interfering regulatory factor-3 and p38/activating transcription factor-2 pathways." (PMID 35682866, 2022).
astrocytoma (1 paper, 2023). "Furthermore, it was found that there were specific binding sites of positive regulatory elements of nuclear factor kappa B (NF-κB) and ATF-2, which located the upstream the promoter region of TIMP-1 in the study of astrocytoma." (PMID 36690987, 2023).
B cell lymphoma (1 paper, 2022). "ATF2’s function in regulating B cell lymphoma progression has been well illustrated in previous studies." (PMID 34996354, 2022).
basal cell carcinoma (1 paper, 2013). A carcinoma involving the basal cells. "This is consistent with the observation of reduced ATF2 and increased β-catenin in human squamous and basal cell carcinoma samples and suggests that ATF2 suppresses epidermal carcinogenesis." (PMID 23762562, 2013).
bladder tumors (1 paper, 2020). "In bladder tumor specimens, significant correlations between immunoreactivities to AR versus ATF2 or phospho-ATF2 were observed." (PMID 32759680, 2020). "Immunohistochemistry in transurethral resection specimens also showed significant elevation of the expression of ATF2, phospho-ATF2 and phospho-ERK in bladder tumors, compared with non-neoplastic urothelial tissues." (PMID 32759680, 2020).
bone tumor (1 paper, 2021). "KCNQ1OT1 serves as ceRNA to regulate multidrug resistance via regulating miR-27b-3p/activating transcription factor 2 (ATF2) in human chordoma bone tumor cells." (PMID 34827600, 2021).
cardiomyopathy (1 paper, 2021). A disease of the heart muscle or myocardium proper. "Thus, while our results point toward ATF2 as a novel FBXO32 target, further experiments are required to establish the direct link between ATF2 and the cardiomyopathy caused by the FBXO32 mutation." (PMID 34272480, 2021). "Our findings highlight a critical mechanism underlying the pathogenesis of DCM and suggest that targeting CHOP or perhaps ATF2 should be considered as an approach for the treatment of DCM and in particular the cardiomyopathy due to the FBXO32 mutation." (PMID 34272480, 2021).
cerebral malaria (1 paper, 2020). A sequestration of Plasmodium falciparum in the brain, which can cause coma and/or seizures. "This miR-Ago2 could down-regulate the expression of CAV-1 and ATF2 resulting in endothelial cells alteration which is a plausible factor contributing vascular dysfunction in cerebral malaria." (PMID 32778117, 2020).
cholangiocarcinoma (1 paper, 2022). A carcinoma that arises from the intrahepatic biliary tree (intrahepatic cholangiocarcinoma) or from the junction, or adjacent to the junction, of the right and left hepatic ducts (hilar cholangiocarcinoma). "ATF2 was speculated to mediate the suppressor role of miR-451 in cholangiocarcinoma." (PMID 36352360, 2022).
chronic lymphocytic leukemia (1 paper, 2021). "The microtubule disrupting agent BNC105 could lead to rapid apoptosis and result in activation of JNK/ATF2 pathway in chronic lymphocytic leukemia cells." (PMID 34037092, 2021).
ciliopathy (1 paper, 2022). A genetic disorder of the cellular cilia or the cilia anchoring structures, the basal bodies, or of ciliary function. "Future studies could concentrate on the role played by ATF2 and its targets in the shared etiology of ciliopathies and HLHS." (PMID 35456433, 2022).
COVID-19 (1 paper, 2023). A disease caused by infection with severe acute respiratory syndrome coronavirus 2. "TF enrichment analysis revealed upregulation of fibrotic-associated ATF2, STAT3, and SMAD family TFs across MLCs in PPASC compared to severe COVID-19." (PMID 38259488, 2023).
cytomegalovirus infection (1 paper, 2018). A herpesvirus infection caused by Cytomegalovirus. "For instance, IRFs and ATF2 (in addition to NF-κB) were associated with cytomegalovirus infection which is consistent with these TFs being activated by viral pathogens through pattern recognition receptors." (PMID 30184180, 2018).
dilated cardiomyopathy (1 paper, 2021). Cardiomyopathy which is characterized by dilation and contractile dysfunction of the left and right ventricles. "Additional research will be necessary to elucidate the precise molecular mechanism by which CHOP inhibits autophagy in dilated cardiomyopathy cases that are linked to ATF2-dependent induction of CHOP-induced apoptosis." (PMID 34272480, 2021).
endometriosis (1 paper, 2021). The growth of functional endometrial tissue in anatomic sites outside the uterine body. "In endometriosis, the levels of MEG3-210 are downregulated and the levels of free Galectin-1 are upregulated, which is associated with the subsequent activation of p38 MAPK signaling–mediated phosphorylation of ATF2." (PMID 34768856, 2021). "Activated ATF2 increases the expression of BCL-2 and MMP contributing to the anti-apoptotic, pro-migratory, and invasive phenotype of endometriosis cells." (PMID 34768856, 2021).
enteritis (1 paper, 2022). Inflammation of the small intestine. "The activating transcription factor 2 (ATF2) targeted the REG4 promoter to induce REG4 expression during enteritis." (PMID 36172286, 2022).